EGFR (epidermal growth factor receptor)
Diseases named in the same sentence as EGFR in open-access papers (continued):
Sharing a sentence is not in itself a finding about the gene and the disease.
glioma (continued). "This analysis aimed to elucidate the molecular interactions of mucins with IDH1 and MGMT via EGFR, providing insights into their potential roles in glioma-related pathways and broader biological processes, and the resulting PPI enrichment p-value was <1.0 × 10−16, ranging from 0.99 to 0.42." (PMID 39767713, 2024). "On the other hand, multiple miRNAs have been identified to target oncogenes and play tumor suppressive roles as is the case for miR-7 (downregulated in GBM) by targeting PI3K and Raf-1 via the EGFR pathway, and miR-128 was found to decrease glioma cell proliferation by targeting E2F3a." (PMID 39055532, 2024). "Therapeutics directed against EGFR have been extensively employed in glioma therapy." (PMID 39722126, 2024). "In this study, prevalence of functional EGFR fusions was 0.303% (106/35,023) in total across solid tumors, which occur more commonly in gastroesophageal junction cancer (1/61, 1.613%), followed by medulloblastoma (1/66, 1.515%) and glioma (33/2409, 1.370%)." (PMID 39054543, 2024). "The microtubule-associated protein TAU is highly expressed in IDH-mutant gliomas, which is detrimental to gliomas without EGFR mutations because it inhibits angiogenesis." (PMID 38365669, 2024). "Some biological markers suggest that gliomas may have more drug options, such as IDH mutation, EGFR amplification, and BRAF V600E mutations." (PMID 39118481, 2024). "EGFR amplification in gliomas is commonly defined by an EGFR/CEP7 ratio of ≥2." (PMID 38605523, 2024). "Amplification of EGFR and active mutant EGFRvIII occurs frequently in gliomas." (PMID 39722126, 2024). "Of 28 genes identified as hallmark EGFR signaling cascade genes, 21 demonstrated significant 3′ UTR lengthening, 7 displayed no change and 1 displayed significant shortening in APC low expression low-grade glioma samples." (PMID 39375704, 2024). "Although EGFR and EGFR mutations are prevalent in HGG, EGFR-targeting tyrosine kinase inhibitors (TKIs) and antibodies have not significantly improved survival in glioma patients." (PMID 39877359, 2024). "Furthermore, overexpression of CMTM1 in the glioma cell line A172 promotes tumor cell proliferation and migration, possibly through activation of epidermal growth factor receptor (EGFR), SRC kinase, and WNT signaling pathways." (PMID 38223763, 2024). "Antisomatostatin 2 receptor peptide-based targeted delivery of encapsulated 3,3′-diindolylmethane (antitumor compound) nanoparticles prevents the progression of gliomas; this procedure promotes apoptosis and abrogates the activation of the epidermal growth factor receptor pathway in glioma cells." (PMID 39063232, 2024). "Notably, the epidermal growth factor receptor (EGFR) and the Wnt/β-catenin pathways have been also shown to interact and synergize during glioma tumorigenesis." (PMID 38473403, 2024). "Furthermore, genetic alterations in EGFR of glioma G2 grade lead to abnormal mitogen-activated protein kinase (MAP kinase) pathway signaling." (PMID 38254732, 2024). "Compound 59 was a promising orally accessible anti-glioma drug that targeted EGFR and could pass through the BBB." (PMID 38686058, 2024). "However, the expansion cohorts for afatinib 180 mg every 4 days and 280 mg every 7 days required enrollment of high-grade glioma with EGFR aberrations." (PMID 38680990, 2024). "Cetuximab and other EGFR inhibitors, however, have a limited effectiveness in treating gliomas." (PMID 39850823, 2024).
glioma (continued). "Moreover, our study contributes to the growing body of evidence associating LRIG1 with glioma pathogenesis, corroborating previous research highlighting LRIG1’s inhibitory effects on EGFR expression and downstream signaling pathways." (PMID 38790164, 2024). "For example, circular E-cadherin encoded protein activates epidermal growth factor receptor (EGFR) independent of EGF to maintain glioma stem cell oncogenicity." (PMID 39550559, 2024). "In glioma, EGFR signaling supports the connection of mucins to molecular classification." (PMID 39767713, 2024). "EGFR and VIM are markers previously associated with proliferative glioma cells." (PMID 38275289, 2024). "Thus, further exploration of EGFR Amp in IDH-mutant gliomas should be considered in tumors of specific grade or together with other genetic alterations." (PMID 38595969, 2024). "The influence of certain genes, such as DNA2, EGFR, FAIM, and HEATR3, on glioma risk, which is mediated through alterations in telomere length, enhances the elucidation of pathogenic mechanisms and introduces novel strategies for targeting telomere‐related pathways." (PMID 39722126, 2024). "In addition, EGFR + TNF inhibition is more effective than temozolomide treatment in glioma cells where methylguanine methyltransferase (MGMT) is unmethylated, whereas it is comparable in MGMT methylated cells." (PMID 38561856, 2024). "Specifically, we observed only 3, 0, and 1 EGFR-amp among Grade 2, 3, and 4 gliomas, respectively." (PMID 38893240, 2024). "Numerous studies have shown that the role of autophagy in tumors can be effectively leveraged, and several regulatory factors, such as PTEN and EGFR, can not only inhibit growth but also enhance tumor sensitivity to drugs, offering new avenues for future glioma treatment." (PMID 38304870, 2024). "Aberrant EGFR signaling is a major driver of glioma invasion and angiogenesis." (PMID 39722126, 2024). "The underlying mechanism was explored by network pharmacology and western bolt experiments, which indicated that compound 1 could induce glioma cells LN229 apoptosis by regulating the EGFR/PI3K/Akt/mTOR pathway." (PMID 37108310, 2023). "As a result, it is necessary to have a deeper understanding of the modulation of the EGFR pathway, and the upstream regulation mechanism of EGFR signaling in gliomas remains unclear." (PMID 37759950, 2023). "For example, GBP2 accelerated the proliferation and migration of glioma via KIF22/EGFR pathway." (PMID 37622120, 2023). "Interestingly, co-delivery of DOX and EGFR siRNA in intracranial U87MG xenografts prolonged the life span of glioma-bearing mice and induced apoptosis in gliomas, which is exactly the combination we recommend based on our results." (PMID 36900355, 2023). "Targeting STAT3 sensitizes glioma cells to anti-EGFR (Iressa/gefitinib) and alkylating agents." (PMID 36900355, 2023). "The epidermal growth factor receptor/extracellular signal-regulated kinase/p38/mitogen-activated protein kinase (EGFR/ERK/p38 MAPK) signaling pathway affects glioma proliferation and apoptosis, and AQP9 is involved in the oxidative phosphorylation pathway in glioma cells." (PMID 37280594, 2023). "By comparing the top 20 genes with highest frequency of somatic mutations in low- (n=441) and high-risk (n=203) group, we found that higher frequency of IDH, ATRX, and CIC mutations in gliomas with low LRS risk, while mutations of EGFR, PTEN, and NF1 were more frequent in the high-risk group." (PMID 36860853, 2023). "Further proteogenomic integrative analysis combined with functional experiments highlight the cis-effect of EGFR alterations might lead to glioma tumor cell proliferation through ERK5 medicates nucleotide synthesis process." (PMID 36720864, 2023).
glioma (continued). "Interestingly, a tumor suppressive circular RNA, circ-EGFR, antagonizes miR-183-5p and act as a sponge to sequester miR-183-5p and ultimately inhibits glioma progression through rescuing TUSC2 expression." (PMID 37173921, 2023). "However, almost all relevant clinical trials on various EGFR tyrosine kinase inhibitors (TKIs) for primary and recurrent glioma patients have yielded little success." (PMID 37408388, 2023). "Many studies have shown that glycosylation-related enzymes in gliomas can influence EGFR function." (PMID 37231524, 2023). "Also, amplification of the epidermal growth factor (EGFR) and loss of phosphatase and tensin homolog (PTEN) can contribute to the malignant phenotype of glioma and the downstream targets, Akt and NF-kB, impact oncogenesis, cell proliferation and apoptosis." (PMID 36302993, 2023). "In conclusion, all these data suggested that compound 1 treatment could inactivate EGFR/PI3K/Akt/mTOR signaling in glioma cells LN229." (PMID 37108310, 2023). "Whether KIDINS220 could be part of the stimulus-response threshold activating this pro-survival pathway downstream of EGFR in glioma stem cells and possible therapeutic implications, deserves further investigation." (PMID 37542079, 2023). "Moreover, overexpression of circ-EGFR led to increased apoptosis, decreased proliferation, migration and invasion of glioma cell lines through inhibition of miR-183-5p and ultimately the restoration of TUSC2 expression." (PMID 37173921, 2023). "Research has reported that EGF could induce STAT1 expression to exacerbate the IFN-γ-mediated PD-L1 axis in EGFR-positive cancer cell lines, excluding glioma, and blockade of EGFR by afatinib inhibited EGF- and IFN-γ-mediated PD-L1 expression." (PMID 37759950, 2023). "The most common EGFR copy number alterations in glioma is the polysomy of the entire chromosome 7." (PMID 37446288, 2023). "This leads to overexpression of EGFR protein and increased tumorigenesis and progression of glioma." (PMID 37687164, 2023). "As a title of example, lapatinib is in a clinical trial for a number of solid tumors sharing the features of high EGFR and/or HER1/2 expression, particularly high-grade gliomas (NCT02101905), prostate cancer (NCT00246753), and head and neck cancers (NCT01044433)." (PMID 37627201, 2023). "In addition, the results of flow cytometry and western bolt experiments confirmed that compound 1 induces glioma cell apoptosis by regulating the EGFR/PI3K/Akt/mTOR pathway." (PMID 37108310, 2023). "First, the effects of inhibition of EGFR on glioma cells were analyzed." (PMID 36900355, 2023). "EGFR is commonly upregulated in gliomas and leads to uncontrolled proliferation." (PMID 36768856, 2023). "Some studies have mentioned the positive impact of FOXM1 on the expression of growth factors, including vascular endothelial growth factor (VEGF) and epidermal growth factor receptor(EGFR) in high-grade gliomas, all necessary for the growth and proliferation of GSCs." (PMID 37821870, 2023). "9L glioma cells treated by M146-exo showed a decrease in EGFR and NF-kB protein levels." (PMID 36839879, 2023). "In addition, EGFR amplification (especially EGFRvIII) and TERT mutation have gained a key role in recognizing low-grade glioma IDH-wildtype, potentially associated with the worst prognosis and more aggressive behavior." (PMID 36765898, 2023).
glioma (continued). "Therefore, EGFR plays a key role in the development and progression of glioma due to its involvement in regulating the proto-oncogene MYC family and in promoting the glutamine metabolism via ELK1 activation." (PMID 37446288, 2023). "The findings in this study indicated that compound 1 could be a potential inhibitor of EGFR for the treatment of glioma." (PMID 37108310, 2023). "The result of network pharmacology screening indicated that EGFR might be the potential target of Paris saponins against glioma cells." (PMID 37108310, 2023). "For instance, ecDNA is a mechanism for EGFR amplification in gliomas." (PMID 37636316, 2023). "Our data implied that the EGFR alterations could directly enhanced the PD-L1 expression though ERK-NFκB signaling pathway in glioma." (PMID 36720864, 2023). "Due to the minor effect of TMZ or DOX alone on glioma cell viability, we explored whether blocking EGFR signaling with the specific inhibitor AG1478 (AG) would modify the cell response to the drugs." (PMID 36900355, 2023). "We further investigated the relationship between the clinicopathological features of patients with glioma and found that the expression of WEE2-AS1 was positively correlated with WHO grade, histological type, IDH status, 1p/19q codeletion status, and EGFR status of patients with glioma." (PMID 36747161, 2023). "The in vivo localization of this dendrimer 1c-G5 after injection into the tumor of rats bearing intracerebral implants of F98 wild-type (F98WT) receptor (−) or EGFR gene-transfected F98EGFR glioma cells demonstrated a much larger localization in F98EGFR versus in F98WT gliomas." (PMID 37631334, 2023). "Notably, this study revealed that IFN-γ can indeed upregulate the phosphorylated form of EGFR, indicating that this pro-inflammatory cytokine can serve as an upstream inducer of the EGFR pathway in gliomas." (PMID 37759950, 2023). "Numerous clinical trials have been introduced attempting to improve the treatment of glioma, including growth factor receptor inhibition, both EGFR and fibroblast (FGFR); apoptotic pathway regulation; angiogenic targets; and several immunotherapeutic approaches." (PMID 37291277, 2023). "Mechanistically, network pharmacology and transcriptomics approaches illustrate that the EGFR/MAPK signaling pathway may be responsible for the inhibitory effect of β-sitosterol on glioma." (PMID 38143380, 2023). "Moreover, Pin1 expression in gliomas is known to increase in correlation with tumor grade, similar to EGFR expression." (PMID 36766769, 2023). "For example, AZD3759 has been reported to inhibit glioma by blocking the EGFR and JAK pathways." (PMID 37928523, 2023). "On the contrary, EGFR mutations frequency in G2 group were higher than those in G1 group, suggesting that the high expression of EGFR may be related to the proliferation of glioma cells." (PMID 37322408, 2023). "The epidermal growth factor receptor (EGFR) is gliomas’ most commonly overexpressed protein." (PMID 38111705, 2023). "Whether there exist factors within the TME that can lead to EGFR activation in the context of gliomas is currently unexplored." (PMID 37759950, 2023). "Conversely, BRAF alterations are rarely found in adult gliomas, although activation of the MAPK is seen in 70% of GBM through amplifications or fusions in EGFR/PDGFRA/MET/FGRF1/2/3 genes or mutations in MAPK pathway members particularly NF1, reported in 15% of GBM." (PMID 37124503, 2023).
glioma (continued). "EGFR has been previously implicated in therapeutic interventions for GBM, while PTEN is a key mechanism and actionable target associated with radiation resistance in gliomas." (PMID 37795080, 2023). "In addition, IFI30 promoted the EMT‐like process in gliomas via the EGFR/AKT/GSK3β/β‐catenin signaling pathway both in vitro and in vivo." (PMID 37408388, 2023). "BCLAF1 acts in a positive feedback loop enhancing PDGFRa and EGFR signaling in high-grade glioma." (PMID 37579831, 2023). "Although the relationship between purine metabolism and EGFR remained unclear, our study found clues and might provide a novel direction for applications of EGFR-targeted therapies in glioma and overturn previous failures." (PMID 36438805, 2022). "It was suggested that GALNT2 modulated the O-glycosylation of EGFR in glioma." (PMID 36058918, 2022). "Based on the cell markers, cluster 0 overexpressing PDGFRA and cluster 2 overexpressing EGFR could be annotated as glioma cells." (PMID 36276141, 2022). "The epidermal growth factor receptor (EGFR), the platelet-derived growth factor receptor (PDGFR), and the MET factor are the most commonly deregulated receptor tyrosine kinases (RTKs) associated with glioma." (PMID 36358663, 2022). "In the glioma cells, the EGFR signaling pathway was decreased via reduction of the STAT3, ERK, and AKT cascade, while iPA inhibited the farnesyl diphosphate synthase (FDPS) activity via reduction of protein prenylation, thus arresting the proliferation of thyroid cancer cells." (PMID 36551529, 2022). "Therefore, EGFR has a guiding role in the diagnosis of glioma, and EGFRvIII can be used to distinguish high-grade gliomas and poor prognosis of patients." (PMID 36040678, 2022). "DBRTG glioma cells treated with curcumin did not alter the level of EGFR and the activity of its associated downstream pathways (RTK/RAS/PI3K) in the cytosol." (PMID 36268515, 2022). "We discovered that miR-450-5p expression was elevated in big follicles and that high levels of miR-450-5p might target EGFR to regulate autophagy in order to increase glioma treatment biosensitivity." (PMID 36613843, 2022). "We hypothesized that combinations of genes IDH1/2, 1p19q, TERTp, EGFR, BRAF, TERTp, 10q, and H3 status can stratify gliomas for risk and may even be superior to conventional histological grading for prognostication." (PMID 35558510, 2022). "All identified gliomas with EGFR amplification were of CNS WHO Grade 4 (seven cases)." (PMID 35453544, 2022). "Thus, the STAT3-dependent (as well as SOX2- and TCF3-dependent) increase in ERRFI1 expression provides the common glioma path for the regulation of EGFR signaling." (PMID 36231068, 2022). "In contrast, SHP2 inhibits cell survival behavior in liver cancer, colon cancer, metachondromatosis, and esophageal squamous cell carcinoma and facilitates cell death of glioma cells induced by co-inhibition of epidermal growth factor receptor (EGFR) and c-Met." (PMID 36002018, 2022). "Another PARP-1 inhibitor, talazoparib, increased DNA damage and PARP–DNA trapping, enhancing cytotoxicity against EGFR-amplified glioma sphere-forming cells, Additionally, it reduced tumor growth significantly in EGFR-amplified subcutaneous models but not in nonamplified models." (PMID 35873570, 2022). "Thus, we focused on large glioma dataset studies, searching for the specific co-occurrence of IDH mutation and EGFR amplification." (PMID 35669011, 2022). "Treatment of glial tumors aim to suppress the expression of the tumor EGFR." (PMID 35745855, 2022). "Detailed analysis showed that EGFR amplification is unevenly distributed across gliomas." (PMID 35453544, 2022). "The heterogeneity of EGFRs in glioma might be an essential reason for the failure of anti-EGFR therapy in glioma." (PMID 36267281, 2022). "EGFR gene alterations are present in approximately 25% of gliomas." (PMID 35267432, 2022).